PTH (parathyroid hormone)
Diseases named in the same sentence as PTH in open-access papers (continued):
Sharing a sentence is not in itself a finding about the gene and the disease.
osteoporosis (continued). "Parathyroid hormone (PTH) has been used to treat osteoporosis in clinical practice due to its ability to activate both osteoblasts and osteoclasts." (PMID 36996343, 2023). "Teriparatide (PTH), abalopathide (PTHrP), and romosozumab (sclerotin antibody) are anabolic drugs approved for the treatment of osteoporosis." (PMID 37576993, 2023). "The intravenous or subcutaneous injection of anti-osteoporosis drugs is usually used to promote the healing of osteoporotic fractures, mainly including bisphosphonates, estrogen, PTH, etc.." (PMID 37622974, 2023). "Human trials have proved these abilities, and PTH itself is already used in the therapy of osteoporosis." (PMID 36984115, 2023). "None of the analytical parameters, including calcium, phosphorus, 25-hydroxyvitamin D, PTH, CTX, and BAP, were associated with a higher risk of osteoporosis." (PMID 38202195, 2023). "Parathyroid hormone and its analogues are a new class of anabolic therapy for severe osteoporosis, and they can improve bone microstructure." (PMID 37197158, 2023). "The change in PTH level occurs as a physiologic response to low levels of vitamin D and leads to high bone turnover, bone resorption, and osteoporosis." (PMID 37298368, 2023). "In contrast, large values of alkaline phosphatase and parathyroid hormone increase the probability of diagnosis in the osteoporosis group." (PMID 36482780, 2023). "Nowadays, there are many pharmacologic treatments for osteoporosis such as bisphosphonates, estrogen-related therapies, parathyroid hormone analogs, and RANK-ligand inhibitory antibodies." (PMID 37445982, 2023). "Vitamin D also plays a role in preventing autoimmune diseases and pain, managing glucocorticoid-induced osteoporosis, and decreasing parathyroid hormone activity, followed by positive effects on pain." (PMID 37686757, 2023). "Chronic kidney disease (CKD) is associated with the development of the mineral and bone disorder (MBD), osteoporosis, and fragility fracture, characterized with abnormal serum levels of calcium, phosphorus, parathyroid hormone (PTH), and vitamin D." (PMID 37089533, 2023). "At present, PTH, PTHrP, and sclerostin antibodies for the treatment of osteoporosis are all protein drugs that have defects such as immunogenicity, easy degradation, high price, short half-life, and poor permeability." (PMID 37576993, 2023). "Currently, drug therapy for osteoporosis includes calcium supplements, vitamin D, parathyroid hormone, estrogen, calcitonin, bisphosphates, and other medications." (PMID 37214253, 2023). "An increase in PTH measurements as part of the workup for low bone mass and diagnosis of osteoporosis helped discover this biochemical phenotype where calcium levels consistently remain normal." (PMID 38115826, 2023). "Treatment of osteoporosis with denosumab in patients with decreased kidney function (eGFR 9–50 mL/min), with normal/high PTH levels, seems in general to be well tolerated, with improvement of bone and decreased risk of new fractures." (PMID 37495795, 2023). "The risk of osteoporosis and fracture increases due to increased vitamin D deficiency (VDD)-induced parathyroid hormone (PTH)." (PMID 38222239, 2023). "Our data support further investigation into the clinical use of PTH/teriparatide and cinacalcet in patients with diabetes and osteoporosis." (PMID 36754901, 2023). "As is known that, excessive secretion of PTH can increase the bone conversion rate and enhance the decomposition and absorption of bone, resulting in osteoporosis." (PMID 36597085, 2023). "Treatment with denosumab of osteoporosis in patients with decreased kidney function (eGFR 9–50 mL/min), with normal/high PTH, seems in general to be well tolerated, with improvement of bone and decreased risk of new fractures." (PMID 37495795, 2023). "Commonly used drugs for the treatment of weightless induced osteoporosis include bisphosphonates, parathyroid hormone, calcitonin and traditional Chinese medicine." (PMID 36617569, 2023).
osteoporosis (continued). "We then introduce perturbations of both the tonic and pulsatile components of PTH secretion to mimic various disease states including osteoporosis and hyperparathyroidism." (PMID 36996072, 2023). "The involvement of high PTH levels in vascular calcification, osteoporosis and malnutrition indicated the need of treating hyperparathyroidism early in patients awaiting kidney transplantation." (PMID 37093441, 2023). "To address this question, we investigated the effects of PTH1-34, a peptide of parathyroid hormone analog and a well-recognized effective anabolic therapy drug for patients with osteoporosis, on 5XFAD animal model." (PMID 36918976, 2023). "Parathyroid hormone (PTH) is an anabolic drug approved by the United States FDA for the treatment of osteoporosis." (PMID 37446790, 2023). "Anti-osteoporosis drugs such as estrogen, raloxifene, bisphosphonates, calcitonin, and parathyroid hormone (PTH) are commonly used in clinical practice." (PMID 37849727, 2023). "The treatment of DTC patients with osteoporosis using active vitamin D, bisphosphonate, calcitonin, estrogen, vitamin K, recombinant human parathyroid hormone, and deslizumab needs further investigation." (PMID 38075039, 2023). "PTH is interesting as it is safely used in the treatment of osteoporosis already and therefore has an established safety profile for that indication." (PMID 36718389, 2023). "Correlation analysis indicated that ToVD levels were significantly correlated with parathyroid hormone levels, BMD, risk of osteoporosis (OP) and the concentration levels of other bone metabolism markers (p < 0.05)." (PMID 37180138, 2023). "These systemic interventions for osteoporosis can promote new bone formation; however, the treatment window for PTH is limited, with most courses lasting 18–24 months." (PMID 36754901, 2023). "In recent years, the rise in neck imaging studies and calcium measurements for osteoporosis screening has contributed to a growing trend of diagnosing patients with pHPT, including patients with low baseline levels of PTH." (PMID 37627880, 2023). "Although estrogen, calcitonin, parathyroid hormone, and bisphosphonates have been widely used to against osteoporosis, there are still limitations exist in the treatment of osteoporosis." (PMID 37032340, 2023). "Studies in adult mice have shown that parathyroid hormone (PTH) can prevent GC-induced osteoporosis, possibly by blocking osteoblast and osteocyte apoptosis." (PMID 37082116, 2023). "In this instance, the parathormone (PTH) levels are extremely elevated, and the clinical pattern is characterized by widespread osteoporosis with sub-periosteal bone resorption and the resultant weakening of the bone–tendon junction." (PMID 38138284, 2023). "PHPT, characterized by an unregulated overproduction of parathyroid hormone (PTH), often causes a decrease in bone mineral density (BMD), leading to osteoporosis and heightened fracture risk." (PMID 39239219, 2023). "Teriparatide, a synthetic PTH analog, which contains the first 34 residues of parathyroid hormone (PTH 1-34), is often used for treating osteoporosis." (PMID 37187628, 2023). "Although PTH1-34 is a therapeutic medicine for osteoporosis, studies emerged in recent years implicate PTH in neurodegenerative diseases." (PMID 36918976, 2023). "Persistent exposure of bone to parathyroid hormone stimulates osteoclast action, leading to increased bone resorption and potentially exacerbating osteoporosis." (PMID 39239219, 2023). "The study included postmenopausal women with osteoporosis, who were treated with either alendronate or parathyroid hormone for 48 weeks." (PMID 37690031, 2023). "PTH1R regulates calcium homeostasis and bone development through the activation of parathyroid hormone (PTH) and PTH-related peptide (PTHrP) and is a target for existing drugs that treat osteoporosis." (PMID 37567868, 2023).
osteoporosis (continued). "Without sufficient dietary calcium intake, the calcium concentration in plasma would decrease; boosting the release of parathyroid hormone (PTH) and induced bone resorption; hence increasing the risk of osteoporosis due to low bone mineral density." (PMID 37375572, 2023). "The major limitation of this study was the lack of measurement of parameters involved in the pathogenesis of osteoporosis, such as PTH, FGF23, OPG, RANK, and RANKL." (PMID 37507659, 2023). "Due to increasing neck imaging studies, and calcium measurements for osteoporosis screening, a growing number of patients with pHPT are diagnosed with low baseline levels of PTH." (PMID 37627880, 2023). "Our analysis revealed miR-146a-5p, miR-551b-5p, miR-205-3p, miR-33a-3p, miR-338-5p and miR-410-3p as PTH-regulated miRNAs, which were also enriched in pathways known to play a part in bone biology and osteoporosis (Supplement S1)." (PMID 36011354, 2022). "The outcome of the present study conclusively demonstrated the potential of the QbD concept to build quality in PTH-LPs with improved osteoanabolic therapy in osteoporosis." (PMID 36365235, 2022). "PTH and its analogues have been used in clinics and ongoing clinical trials to improve osteoporosis." (PMID 35265269, 2022). "The specific anti-osteoporosis drugs’ distribution was similar between groups: 47% were on BPs, 51.5% on denosumab, and 3–5% on PTH analogs (p > 0.9999)." (PMID 36251126, 2022). "Several studies have demonstrated the curative effect of intermittent PTH treatment on osteoporosis of the femoral neck." (PMID 35090461, 2022). "Regarding the treatment of osteoporosis, bisphosphonates and recombinant human parathyroid hormone produce their therapeutic effects via either anabolic or anti-resorptive function, with limitation of long-term treatment due to their adverse effects." (PMID 35777359, 2022). "Hormone disorders (e.g., insulin, parathyroid hormone, etc.)are also positively related to skeletal diseases, such as osteoporosis, osteoarthritis, and acromegaly." (PMID 36188222, 2022). "As the first anabolic agent approved for the treatment of osteoporosis, PTH stimulates the proliferation and osteogenic differentiation of osteoblast precursor cells." (PMID 35462909, 2022). "Pathophysiology of PHPT is reportedly manifested by the increased PTH secretion, high calcium, low phosphorus, decreased calcium sensitivity, osteoporosis, kidney stones, and cardiac diseases." (PMID 35681135, 2022). "In implant treatment, primary stability and osseointegration are improved by continual intermittent administration of parathyroid hormone (PTH) in patients with osteoporosis." (PMID 35675357, 2022). "miRNAs have been well studied for their potential use as osteoporosis biomarkers in previous studies, but in the case of the treatment of osteoporosis with PTH, only two studies have been conducted in terms of determining a potential circulating biomarker." (PMID 36011354, 2022). "If parathyroid hormone continues to rise and hyperthyroidism occurs, it can lead to osteopenia and osteoporosis." (PMID 36793515, 2022). "Regardless, a mix of PTH and bisphosphonates comes out to be a proper therapy for osteoporosis; PTH medicine taken after bisphosphonate treatment gives a fruitful outcome as monotherapy with an antiresorptive drug." (PMID 36381723, 2022). "Compared to subjects in U-CP, those belonging to FLS-CP showed higher adherence to vitamin D supplementation plus calcium, to specific anti-osteoporosis drugs, i.e., BPs, denosumab, or PTH analogs, and complete anti-osteoporosis treatments in all time points." (PMID 36251126, 2022). "Teriparatide, a derivate of PTH, has been used for the treatment of several bone-related diseases such as osteoporosis, because of its superiority in bone formation and anabolic activity." (PMID 35792789, 2022).
osteoporosis (continued). "Nonetheless, glucocorticoids, immunosuppressant cyclosporin A (which induces vascular disease and osteoporosis), prostaglandin E2, fibroblastic growth factor, and parathyroid hormone (PTH) reduce OPG expression." (PMID 36330454, 2022). "PTH is used in the treatment of severe osteoporosis, such as steroid-induced osteoporosis, and has the strongest suppressant effect on vertebral body bone fracture among all osteoporotic therapeutic drugs." (PMID 35675357, 2022). "Oxidized lipid accumulation in bone tissues attenuates osteogenic differentiation and parathyroid hormone resistance, both of which promote osteoporosis." (PMID 36093833, 2022). "Although PTH is a common agent used to prevent osteoporosis, long-term administration of high dose PTH has been related with disruption of osteoblast function." (PMID 36371202, 2022). "To date, the reduction of bone mass due to osteoporosis have been treated by different approaches including bisphosphonates, PTH, denosumab, and romosozumab that still have the limitations of treating osteoporosis." (PMID 35013196, 2022). "Given the ability of PTH to improve the bone conversion efficiency, preliminary experiments in rats involving orthodontic treatment have shown that, although PTH cannot promote tooth movement, it can reduce the recurrence rate of osteoporosis." (PMID 36188222, 2022). "The next surge of incidence has been associated with screening and in-depth evaluation of osteoporosis patients via bone density measurements in combination with assessment of calcium and PTH levels to identify secondary osteoporosis." (PMID 35805976, 2022). "The results indicated that intermittent PTH contributed to treating ovariectomized-induced osteoporosis in the cancellous bone and in the cortical bone of the femoral neck of rats." (PMID 35090461, 2022). "This study revealed that intermittent administration of PTH can enhance primary stability and osseointegration in a glucocorticoid-induced rabbit model of osteoporosis." (PMID 35675357, 2022). "Intermittent PTH helped treat ovariectomy-induced osteoporosis of the cancellous bone and cortical bone in the femoral necks of rats." (PMID 35090461, 2022). "Together, we would prefer to suggest a new indication of PTH for patients suffering from both osteoporosis and NAFLD, and a targeted PTH delivery system for liver-specific delivery awaits further investigation." (PMID 36060945, 2022). "Immune diseases are a cause of anemia, and are often accompanied by abnormal metabolism of vitamin D and PTH, leading to osteoporosis." (PMID 36311487, 2022). "Senile osteoporosis is a multifactorial disease, with a central role played by the high levels of PTH." (PMID 35922724, 2022). "Teriparatide induces an expansion of regulatory T cells (Tregs) in humans and mice and these cells seem to participate in the anabolic effect of PTH in murine models of osteoporosis." (PMID 35629903, 2022). "The parathyroid hormone, for example, has been shown to increase bone density in diseases such as osteoporosis." (PMID 35056817, 2022). "Teriparatide is a recombinant peptide of the first 34 amino-N-terminal residues of parathormone (PTH), which is given daily via subcutaneous route for treatment of age-related and glucocorticoid-induced osteoporosis (Drüeke and Massy, 2016)." (PMID 35222037, 2022). "Intermittent PTH helped treat ovariectomy-induced osteoporosis of cancellous bone and cortical bone in the femoral necks of rats." (PMID 35090461, 2022). "Due to its effect on bone metabolism, PTH is viewed as a therapeutic agent for osteoporosis, fractures, and a number of other disorders of bone renewal and regeneration." (PMID 36359914, 2022). "In the next step, we conducted an enrichment analysis for PTH-regulated miRNAs to elucidate the mechanisms of PTH-regulated miRNAs action on pathways that are known to play a role in bone biology and osteoporosis." (PMID 36011354, 2022).
osteoporosis (continued). "The osteoporosis model, in which PTH was administered continuously until implantation, showed a good ISQ value at implantation and was effective in achieving primary stability." (PMID 35675357, 2022). "Parathyroid hormone (PTH) 1–34 is the first anabolic agent approved for the treatment of osteoporosis." (PMID 35462909, 2022). "Studies have suggested that in addition to antiresorptive drugs with bisphosphonates, anabolic drugs, such as those in intermittent PTH treatment, effectively treat osteoporosis." (PMID 35090461, 2022). "Parathyroid hormone (PTH) is a bone anabolic agent which has been approved for treatment of osteoporosis." (PMID 36371202, 2022). "Intermittent administration of PTH is the only clinically authorized therapy that promotes bone formation and is used to treat severe osteoporosis, such as that induced by glucocorticoid administration." (PMID 35675357, 2022). "Lastly, vitamin D metabolism is dependent on Mg as a cofactor, and metabolic balance between PTH and vitamin D has been shown to be closely related to osteoporosis." (PMID 35711538, 2022). "The results suggest that endocrine mechanism play an important role in regulating osteoporosis, The main substances involved in regulation include estrogen, parathyroid hormone, insulin growth factor -1 and serotonin." (PMID 36596003, 2022). "CKD-induced osteoporosis is a systemic disease that can be related to the following (one or more): abnormal calcium metabolism, phosphate, vitamin D, parathyroid hormone (PTH); calcification of soft tissue; and abnormal bone turnover and mineralization." (PMID 34692259, 2021). "Teriparatide is a 1–34 amino-acid fragment derived from human parathyroid hormone (PTH) and is normally used as a bone anabolic therapy for osteoporosis." (PMID 34603064, 2021). "Teriparatide (TPT), the recombinant human 1–34 parathyroid hormone, is a bone anabolic agent that is approved for the treatment of postmenopausal osteoporosis in women, hypogonadal osteoporosis in men, and glucocorticoid induced osteoporosis." (PMID 33420643, 2021). "For example, teriparatide, a recombinant human PTH, has been previously reported to increase cortisol secretion from adrenals of women treated for osteoporosis, and this has been suggested to blunt the anabolic effect of teriparatide." (PMID 34207309, 2021). "Systemic PTH is the only osteoforming agent approved for the treatment of severe osteoporosis in men; it stimulates osteoblastic activity by increasing bone formation, increases trabecular and cortical thickness, and reduces fracture risk." (PMID 35009347, 2021). "For example, administering PTH daily induces an anabolic effect that has been used for the treatment of osteoporosis and has U.S. Food and Drug Administration approval." (PMID 33925324, 2021). "The parathyroid hormone (PTH) analogues, which were also used/tried for osteoporosis treatment, not only accelerated bone synthesis, but also promoted bone degradation in osteoporotic patients." (PMID 34960006, 2021). "Currently, analogs of parathyroid hormone (teriparatide and abaloparatide) represent the most commonlyused class of bone anabolic osteoporosis treatment agents." (PMID 34160349, 2021). "Anabolic parathyroid hormone (PTH), which is commonly used for treating osteoporosis, shifts the balance from osteoclastic to osteoblastic, although it is unclear how these cells are coordinately regulated by PTH." (PMID 33837198, 2021). "Teriparatide (TPTD), a PTH analog, is an effective drug used in severe osteoporosis, with a completely different action than Dmab." (PMID 34093428, 2021). "Parathyroid hormone (PTH 1‐34) is one of the anabolic osteoporosis drugs approved by the Food and Drug Administration in the United States." (PMID 33615575, 2021). "In the last century, an exciting advance in the treatment of osteoporosis was the introduction of the anabolic osteoporosis drug parathyroid hormone (PTH)." (PMID 33657948, 2021).